METTL3 (methyltransferase 3, N6-adenosine-methyltransferase complex catalytic subunit)
Diseases named in the same sentence as METTL3 in open-access papers (continued):
Sharing a sentence is not in itself a finding about the gene and the disease.
bladder cancer (continued). "Bladder cancer (BC) remains challenging due to its recurrence and metastasis, with METTL3-mediated m6 A RNA modification emerging as a key oncogenic driver." (PMID 40778544, 2025). "METTL3 is significantly upregulated in bladder cancer (BCa) and promotes Bca cell proliferation, migration, and invasion." (PMID 39289775, 2024). "This process promotes the processing and maturation of pri‐miR221/222 in bladder cancer and highlights the oncogenic role of METTL3." (PMID 38721006, 2024). "METTL3 facilitates bladder cancer growth and metastasis by suppressing RRAS expression in a YTHDF2‐dependent manner." (PMID 38267969, 2024). "In bladder cancer, METTL3 deletion resulted in reduced m6A abundance in specific regions of tyrosine kinase endothelial (TEK) and VEGF-A mRNA and decreased levels of TEK and VEGF-A mRNA and protein." (PMID 39289775, 2024). "METTL3, as a methyltransferase, affects the proliferation and progression of bladder cancer cells by regulating the m6A modification of RNA." (PMID 39559360, 2024). "In bladder cancer (BCa), Wang and coworkers found that METTL3 ablation in BCa CSCs suppressed tumor angiogenesis by regulating TEK and VEGFA." (PMID 39691597, 2024). "For instance, METTL3 is highly expressed and promotes bladder cancer by promoting the expressions of MYC and AFF4; inhibition of METTL3 reduces bladder tumor cell proliferation, migration, and invasion." (PMID 39457524, 2024). "METTL3 inhibition is a promising direction for targeting immunotherapeutic resistance in bladder cancer." (PMID 39289775, 2024). "The results showed that METTL3 was significantly upregulated in bladder cancer cell lines and was identified as an oncogene." (PMID 37284313, 2023). "Our study proposes a novel METTL3/YTHDF1-RPN2-PI3K/AKT/mTOR regulatory axis in bladder cancer cells." (PMID 37108067, 2023). "In conclusion, this study proposes a novel METTL3/YTHDF1–RPN2–PI3K/AKT/mTOR regulatory axis that affects bladder cancer cell proliferation and cisplatin sensitivity." (PMID 37108067, 2023). "About YTHDF2, the METTL3/YTHDF2 m6A axis promotes tumorigenesis in bladder cancer by mediating degradation of RRAS, SETD7, and KLF4." (PMID 37369946, 2023). "Decreased METTL3 expression increased the sensitivity of Hela cells to cisplatin, and increased METTL3 expression in bladder cancer cells increased the resistance of bladder cancer cells to cisplatin." (PMID 37108067, 2023). "Next, GAS6 expression at both RNA and protein levels was reduced after METTL3 knock‐down in the bladder cancer cell Lines T24 and UMUC3." (PMID 37313656, 2023). "In bladder cancer, METTL3 upregulates PCAT6 expression and increases IGF1R RNA stability by forming the PCAT6/IGF2BP2/IGF1R complex, which activates the NF-KB and PI3K/AKT signaling pathways." (PMID 37996892, 2023). "Specific to urogenital tumors, the carcinogenesis of METTL3 in bladder cancer has been deeply uncovered, but there is still a controversy in kidney cancer." (PMID 37095108, 2023). "In bladder cancer, METTL3 accelerates pri-miR221/222 maturation through m6A modification, which downregulates PTEN expression through miR221/222 binding to its 3’UTR and stimulates proliferation in vitro and in vivo." (PMID 37996892, 2023). "METTL3 in bladder cancer enhanced the maturation of pri-miR221/222, which decreased the expression of PTEN." (PMID 36835633, 2023). "Recently, studies have reported that METTL3 is highly expressed in bladder cancer and degrades SETD7 and KLF4 mRNAs combined with the m6A reader YTHDF2." (PMID 37259333, 2023). "Several studies have reported that the function of m6A methyltransferases in malignancies, as METTL3 accelerates pri-miR221/222 maturation to promote bladder cancer progression, ALKBH5 activates PER1 to inhibit pancreatic cancer progression." (PMID 37807062, 2023). "JNK1 is necessary for the binding of c-Jun to the METTL3 promoter, which was shown to increase the expression of METTL3 and global RNA m6A levels in bladder cancer cells." (PMID 36835633, 2023).
bladder cancer (continued). "Knockdown of METTL3 can significantly inhibit the proliferation, colony formation, migration and invasion of bladder cancer cells in vitro." (PMID 36008936, 2022). "In bladder cancer, METTL3-mediated m6A modification regulates PD-L1 expression, resulting in resistance to CD8 + T-cell cytotoxicity and supporting tumor growth." (PMID 36476503, 2022). "Dysregulation of METTL3 is considered an important factor affecting the progression of various malignant tumors such as endometrial cancer and bladder cancer." (PMID 36569923, 2022). "Since ITGA6 enhances the growth and metastasis of bladder cancer cells, METTL3 knockout leads to reduced adhesion, proliferation, migration and invasion of bladder cancer cells." (PMID 36008936, 2022). "In bladder cancer, METTL3 interacts with DGCR8 to facilitate pri-miR221/222 maturation, which leads to a decrease in PTEN and ultimately promotes cell proliferation." (PMID 36407103, 2022). "METTL3 can also promote the progression of bladder cancer through both the NF-κB and MYC signaling networks since AFF4, IKBKB, and p65 as well as MYC transcripts are methylated and stabilized by METTL3." (PMID 36008936, 2022). "In bladder cancer, METTL3 promoted the m6A-mediated maturation of pri-miR221/222, a PTEN antagonist, resulting in loss of cell cycle control and increased proliferation." (PMID 35350378, 2022). "In bladder cancer, the mutual interaction between METTL3 and YTHDF2 induced the degradation of SETD7 and KLF4 mRNA in the proliferation and metastasis process." (PMID 34996459, 2022). "METTL3 also enhances the binding of pri-miR-221/222 to DGCR8 to regulate bladder cancer proliferation." (PMID 36226036, 2022). "Recent studies showed that METTL3-mediated m6A hypermethylation promotes the progression of bladder cancer by regulating SETD7/KLF4 mRNA expression, pri-mrR221/222 maturation and AFE4/NF-κB/MYC signaling network activation." (PMID 35945641, 2022). "In bladder cancer, the over-expression of METTL3 increases m6A methylation status, regulates the expression of AFF4, promotes its transcription by combining with the promoter region of Sox2, and promotes the self-renewal of cancer stem cells." (PMID 35022030, 2022). "METTL3 can enhance cell adhesion by upregulating ITGA6, which is linked to poor prognosis in bladder cancer." (PMID 36008936, 2022). "Compared with the paracancerous bladder urothelial tissue, the expression of METTL3 in the bladder cancer tissue is increased." (PMID 36008936, 2022). "Analogously to its impact on bladder carcinoma, METTL3 facilitated the pri-miR-1246 maturation process and paved the way for the enhanced metastasis of CRC cells via the MAPK signaling pathway." (PMID 34722298, 2021). "In bladder cancer, METTL3 promoted the maturation of miR-221/222 and accelerated cancer cell proliferation, growth, and stemness." (PMID 34345203, 2021). "METTL3 promoted tumor growth in bladder cancer via modulating pri‐miR221/222 maturation by an m6A‐dependent manner." (PMID 33206457, 2021). "In bladder cancer, for example, upregulation of METTL3 accelerated the processing of pri-miR221/222, which promoted the proliferation, migration, and invasion of cancer cells in an m6A-dependent manner." (PMID 34722298, 2021). "In our study, we found that ablation of Mettl3 in bladder urothelial attenuates the oncogenesis and tumor angiogenesis of bladder cancer using transgenic mouse model." (PMID 33681207, 2021). "Previous studies had shown that m6A-related genes, including METTL3, were negatively correlated with the recurrence of bladder cancer patients." (PMID 34604051, 2021). "Klf4 has been reported to be a downstream target of methyltransferase like 3 (METTL3) using METTL3-depleted T24 bladder cancer cells." (PMID 34195082, 2021).
bladder cancer (continued). "Another study reported that METTL3 was significantly up-regulated in bladder cancer, and its knockdown suppressed in vitro proliferation, invasion, and survival as well as in vivo tumorigenicity of bladder cancer cells." (PMID 33795529, 2021). "The m6A modification catalyzed by Mettl3 has been widely recognized as a critical epigenetic regulation process for tumorigenic properties in various cancer cell lines, including bladder cancer." (PMID 33681207, 2021). "Briefly, common METTL3 expression inhibits the in vivo proliferation of bladder cancer and, conversely, METTL3 overexpression promotes its proliferation in vivo." (PMID 34660577, 2021). "Briefly, low METTL3 expression inhibits the in vivo proliferation of bladder cancer and, conversely, METTL3 overexpression promotes its proliferation in vivo." (PMID 34660577, 2021). "In bladder cancer, m6A expression showed upregulation, and inhibition of METTL3 inhibited proliferation, invasion, and migration of bladder cancer tumor cells." (PMID 34660577, 2021). "A study demonstrated that METTL3 plays an oncogenic role in growth and invasion of bladder cancer cell via AFF4/NF-κB/MYC signaling pathway." (PMID 34521394, 2021). "In bladder cancer, METTL3 elevates the m6A level of CDCP1, enhancing its translation, which is modulated by YTHDF1, and the upregulation of METTL3 and CDCP1 is correlated with poor prognosis of bladder cancer." (PMID 33758623, 2021). "In bladder cancer, METTL3 mediates the m6A modification of the AFF4 gene, which binds to the promoter of MYC and elevates MYC expression to promote cancer progression." (PMID 34315512, 2021). "A recent study found that overexpression of m6A methyltransferase METTL3 facilitates tumor development through AFF4/NF-κB/MYC signal pathway in bladder cancer." (PMID 34367534, 2021). "Third, the anticancer potential of these compounds needs to be studied in renal cell carcinoma, glioblastoma and bladder cancer, where METTL3 plays a tumor suppressor role." (PMID 34315512, 2021). "Consistent findings demonstrated that METTL3 is significantly upregulated in bladder cancer, knockdown of which dramatically repressed cancerous cell proliferation, invasion, and xenograft tumor formation via AFF4/NF-kB/Myc axis signaling pathway." (PMID 33611339, 2021). "In bladder cancer, METTL3 binds to DGCR8 and positively accelerates pri-miR221/222 maturation process, which results in the reduction of PTEN and ultimately increased cell proliferation." (PMID 33611339, 2021). "METTL3 promote tumor proliferation of bladder cancer by accelerating pri-miR221/222 maturation in m[superscript 6]A-dependent manner." (PMID 34521394, 2021). "For example, in bladder cancer, the m6A regulator METTL3 promotes the progression of bladder cancer through the AFF4/NF-kB/MYC signaling network." (PMID 33952279, 2021). "We previously found that METTL3 promotes the carcinogenesis and metastasis of prostate cancer and bladder cancer." (PMID 34326314, 2021). "Largely in agreement with our finding, the oncogenic function of METTL3 has been validated in bladder cancer; METTL3 promotes the maturation of pri-miR-221/222 through mediation of m6A modification." (PMID 33420414, 2021). "METTL3 promoted the proliferation and metastasis of bladder cancer via the AFF4/NF‐κB/MYC signalling network in an m6A‐dependent manner." (PMID 32808488, 2020). "Most of the available research on methyltransferases in bladder cancer suggests that METTL3 is a oncogene, whereas METTL14 is a tumor suppressor." (PMID 32765970, 2020). "Considering oncogenic role in prostate cancer and bladder cancer, METTL3 and YTHDF2 present opportunities for the development of effective targeted therapeutics." (PMID 32808488, 2020). "In contrast, METTL3 knockdown abrogates the proliferation, invasion, and viability of bladder cancer cells and reduces the proportion of cells in the S phase of the cell cycle while increasing the proportion in G1." (PMID 32765970, 2020).
bladder cancer (continued). "In bladder cancer, METTL3 regulates methylation of MYC as well as two specific factors in the nuclear factor-kappaB (NF-κB) pathway to stimulate the overall tumorigenesis." (PMID 33048840, 2020). "The METTL3-DGCR8 (DiGeorge Syndrome Critical Region 8)-pri-mi221/222-PTEN pathway also mediates the upregulation of METTL3 in bladder cancer." (PMID 32765970, 2020). "It has been suggested that METTL3 promotes bladder cancer cell proliferation and invasion by modulating pri-miR-221/222 and the AF4/FMR2 family member 4 (AFF4)/nuclear factor kappa B subunit 1 (NF-κB)/MYC pathway in an m6A-dependent manner." (PMID 32709063, 2020). "Considering the dual role of METTL3 as an oncogene in prostate cancer and bladder cancer and as a tumour suppressor gene in renal cell carcinoma, its underlying mechanisms need to be further studied." (PMID 32808488, 2020). "Corresponded to the detected abnormal m6A modification of MYC mRNA in many cancers, including myeloid leukemia 15, bladder cancer 16, and GBM 29, aberrant MYC expression was also caused by METTL3-mediated m6A modification in PCa." (PMID 32284755, 2020). "Cheng et al31 found that the expression of METTL3 was elevated in bladder cancer and further identified AF4/FMR2 family member 4 (AFF4), key regulators of the NF‐κB pathway (IKBKB and RELA) and MYC as direct downstream targets of METTL3." (PMID 32808488, 2020). "Although most studies suggest that METTL3 can foster bladder cancer growth and progression, one study suggests that METTL3 can act as a bladder tumor suppressor." (PMID 32765970, 2020). "METTL3 has been reported to promote the bladder cancer progression by AFF4/NF-κB/MYC signaling pathway where it upregulates the oncoprotein MYC expression in both direct and indirect manner." (PMID 32194861, 2020). "In bladder cancer, patients with high expression of METTL3 had worse prognosis and shorter survival time, compared with those with low expression of METTL3." (PMID 32513173, 2020). "In bladder cancer, METTL3 regulates pri‐miR221/222 processing in an m6A‐dependent manner to promote carcinogenesis." (PMID 32808488, 2020). "The m6A methyltransferase METTL3 seems to play important roles in the carcinogenesis of bladder cancer." (PMID 32808488, 2020). "METTL3 plays critical roles in both prostate cancer and bladder cancer, and the expression of METTL3 is elevated in these cancers." (PMID 32808488, 2020). "In bladder cancer, increased METTL3 predicts poor survival because with the help of pri-miR221/222, upregulated METTL3 results in downregulated PTEN and tumorigenesis of cancer." (PMID 32303268, 2020). "In patients with bladder cancer, METTL3, which participates in cancer development by accelerating the m6A-dependent maturation of miR-221/222, is related to their poor prognosis." (PMID 32443966, 2020). "The AFF4/NF-κB/MYC (AF4/FMR2 Family Member 4/ Nuclear Factor Kappa B/ Myelocytomatosis oncogene) signaling network plays a vital role in the upregulation of METTL3 in bladder cancer." (PMID 32765970, 2020). "An existing study further demonstrated that METTL3 promotes the expression of MYC in bladder cancer cells by augmenting the m6A modification of MYC mRNA, which was consistent with our findings." (PMID 33048840, 2020). "The ectopic expression of METTL3 potentiates bladder cancer progression through the AFF4/NF‐κB/MYC network." (PMID 33029866, 2020). "Patients with high METTL3 expression in bladder cancer have higher histological scores, worse prognosis, and shorter survival time." (PMID 32765970, 2020). "In bladder cancer (BCa) METTL3 overexpression has been correlated with increased cancer progression." (PMID 32194861, 2020). "In bladder cancer cells, METTL3 and ALKBH5 alter cell adhesion through the m6A methylations of the ITGA6 mRNA 3’UTR20." (PMID 31959747, 2020). "Recent studies noted that METTL3 was drastically upregulated in bladder cancer tissues and was related to tumor histological grade." (PMID 31921660, 2019).
bladder cancer (continued). "The increased m6A modification and translation of oncogene CDCP1 in the transformed uroepithelial cells indicates the potential role of METTL3/m6A/CDCP1 axis in bladder cancer oncogenesis." (PMID 30796352, 2019). "We found METTL3 was upregulated in bladder cancer cell lines, compared with that in the normal urinary epithelial cell line SV-HUC, both in mRNA and protein levels." (PMID 31228940, 2019). "Our data revealed that METTL3 depletion in T24 cells modestly reduced the bladder cancer growth in vivo." (PMID 30796352, 2019). "Quantitative real-time PCR, western blot and immunohistochemistry were used to detect the expression of METTL3 in bladder cancer." (PMID 31228940, 2019). "Then we validated the expression of PTEN in METTL3 knockdown or overexpression bladder cancer cells by qRT-PCR and western blot." (PMID 31228940, 2019). "In summary, our results showed that METTL3 was significantly increased in bladder cancer and correlated with poor prognosis of bladder cancer patients." (PMID 31228940, 2019). "Taken together, METTL3 and CDCP1 expression are upregulated in human bladder cancer samples and the expression of METTL3 and CDCP1 are associated with bladder cancer progression." (PMID 30796352, 2019). "The protein level of METTL3 in bladder cancer tissues also increased significantly, compared with that in the adjacent normal tissues." (PMID 31228940, 2019). "The upregulated METTL3 and CDCP1 in bladder cancers and the correlation between high METTL3/CDCP1 expressions with advanced bladder cancer stages suggested the important function of METTL3-m6A-CDCP1 axis in regulation of bladder cancers." (PMID 30796352, 2019). "In bladder cancer, METTL3 and oncogene CDCP1 are up-regulated, correlating with bladder cancer progression status." (PMID 31801551, 2019). "Then, we verified the expression of miR221/222 and pri-miR221/222 in the METTL3 knockdown and overexpression bladder cancer cells." (PMID 31228940, 2019). "Bladder cancer cells were stably transfected with lentivirus and cell proliferation and cell cycle, as well as tumorigenesis in nude mice were performed to assess the effect of METTL3 in bladder cancer." (PMID 31228940, 2019). "In our study, we firstly verified the expression of METTL3 in six bladder cancer cell lines (EJ, T24, J82, 5637, 253 J, RT4)." (PMID 31228940, 2019). "IHC analysis in bladder cancer tissues showed that the expression of METTL3 was related to tumor histological grade." (PMID 31228940, 2019). "As METTL3 acted as an oncogene in bladder cancer, we selected T24 and EJ cell lines with higher METTL3 expression for our follow-up experiments." (PMID 31228940, 2019). "In the present study, we indeed found METTL3 exhibited its oncogenic role in bladder cancer through interacting with the microprocessor protein DGCR8 and positively modulating the pri-miR221/222 process in an m6A-dependent manner." (PMID 31228940, 2019). "Together, we found that PTEN was negatively correlated with METTL3 expression in bladder cancer tissues." (PMID 31228940, 2019). "In the present study, we found METTL3 promoted bladder cancer proliferation by accelerating the maturation of pri-miR221/222 by an m6A dependent manner, resulting in the reduction of PTEN." (PMID 31228940, 2019). "We experimentally validated METTL3 as a tumor suppressor gene in bladder cancer, providing support to the important role mRNA modification plays in tumorigenesis." (PMID 31363082, 2019). "We also found that METTL3 and miR221/222 were positively correlated in bladder cancer patients’ tissues." (PMID 31228940, 2019). "Then we found that METTL3 was significantly upregulated in bladder cancer cell lines, especially in EJ and T24 cell lines." (PMID 31228940, 2019). "In the present study, we found that METTL3 was required for the engagement of pri-miRNAs by the DGCR8 in bladder cancer." (PMID 31228940, 2019).